BDNF (brain derived neurotrophic factor)
Diseases named in the same sentence as BDNF in open-access papers (continued):
Sharing a sentence is not in itself a finding about the gene and the disease.
neuroblastoma (continued). "By now, BDNF has been studied in several human cancers: neuroblastoma, ovarian, lung, prostate cancer (rather as an oncogene) and breast cancer." (PMID 25036590, 2014). "In the present study, the impact of BDNF on the toxic effects of the Aβ-induced apoptosis was examined via the phosphoinositide 3-kinase (PI3K)/Akt signaling pathway in SH-SY5Y neuroblastoma cells." (PMID 25371750, 2014). "TrkB, sometimes in conjunction with its ligand, BDNF, is often overexpressed in different human cancers including neuroblastomas, Wilms's tumor, and prostate and pancreatic adenocarcinomas, as well as multiple myeloma, a nonsolid tumor." (PMID 24403258, 2013). "PI3K also involved in the prosurvival effects of BDNF in the SH-SY5Y neuroblastoma cell line, as well as in the protective effects of BDNF against cortical neuronal death." (PMID 24086445, 2013). "Consistent with BDNF/TrkB signaling-mediated induction of VEGF-A activity in neuroblastoma cells, levels of VEGF-A mRNA were also decreased in metastatic tumors by the suppression of endogenous TrkB signaling." (PMID 24403258, 2013). "Studies in neuroblastoma cell lines have shown that BDNF stimulation induces TrkB-mediated cell invasion." (PMID 23936232, 2013). "In vitro, long-term chronic ethanol exposure results in reduced BDNF signalling in human neuroblastoma cells." (PMID 25408911, 2013). "To identify phosphatases that regulate BDNF-TrkB-mediated neurite outgrowth we developed a functional siRNA-based screen system using the human neuroblastoma cell line SH-SY5Y." (PMID 23785422, 2013). "RACK1 translocated to the nucleus in glioma and neuroblastoma cell lines upon PKA activation by forskolin to mediate the expression of a brain-derived neurotrophic factor." (PMID 23305203, 2013). "BDNF/TrkB-induced cell proliferation has been reported in other cancers, including neuroblastoma, Wilms’ tumor, and pancreatic adenocarcinoma." (PMID 22911740, 2012). "Due to poor outcomes exhibiting overexpression of BDNF and TrkB in neuroblastomas, increased levels of BDNF and TrkB are also supposed to reflect the prognosis of leiomyosarcoma." (PMID 22911740, 2012). "In SK-N-SH human neuroblastoma cell cultures, BDNF application increased sodium and calcium channel expression, which would increase excitability, whereas NT-3 increased potassium channel expression, which would decrease it." (PMID 22211901, 2012). "Specifically, TrkB activation by BDNF promotes cell growth and induces drug-resistant neuroblastoma phenotypes." (PMID 22911740, 2012). "In support of this, BDNF activation of TrkB has been found to induce vascular endothelial growth factor (VEGF) expression via hypoxia inducible factor-1-alpha (HIF-1-α) in neuroblastoma cells." (PMID 21767406, 2011). "High BDNF expression was reported in neuroblastoma, myeloma, B-lymphocytic leukemia cell lines, bladder cancer, choriocarcinoma or pancreatic cancer." (PMID 21966426, 2011). "A recent study demonstrated that a σ1R agonist indeed potentiates the secretion of brain-derived neurotrophic factor (BDNF) from neuroblastoma cells." (PMID 21904468, 2011). "It was previously shown that BDNF triggers several survival signaling pathways such as PI3-kinase/Akt in neuroblastoma cell lines as well as in embryonic cortical neurons from rats." (PMID 21966426, 2011). "It was reported that the BDNF/TrkB pathway promotes cell survival and protects cells from DNA damaging agents in neuroblastomas cells." (PMID 21966426, 2011). "To better explore the connection between iron and BDNF levels we employed a cell culture model (human SH-SY5Y neuroblastoma cells)." (PMID 21949858, 2011). "Brain-derived neurotrophic factor (BDNF), the primary ligand, binding to TrkB results in the regulation of various cellular activities in neuroblastoma, such as cell differentiation, apoptosis, and invasion." (PMID 20156366, 2010).
neuroblastoma (continued). "Increased angiogenesis, invasiveness and suppression of anoikis resulting from BDNF/TrkB signaling contributes to the aggressive phenotype of neuroblastoma tumors and is a likely mechanism for altered mammary tumorigenesis." (PMID 19173004, 2009). "The sequential use of retinoic acid and BDNF can reproducibly differentiate SH-SY5Y human neuroblastoma cells into cells of neural appearance with extensive neurite outgrowth." (PMID 19735367, 2009). "We studied the effect of different antidepressants on BDNF mRNA expression in human neuroblastoma SH-SY5Y cells." (PMID 18601743, 2008). "In neuroblastoma cells, BDNF is co-expressed with TrkB, suggesting that autocrine stimulation is a means by which proliferation is sustained in the transformed cells." (PMID 17309801, 2007). "PIA6 sensitizes neuroblastoma cells to chemotherapy and attenuates BDNF protection of neuroblastoma cells from chemotherapy-induced cell death." (PMID 19384426, 2007). "Furthermore, research indicated that BDNF protected neuroblastoma cells from Aβ25-35-induced apoptosis by activating PI3K/AKT and phosphorylating GSK3β." (PMID 40430064, 2025). "Brain-derived neurotrophic factor (BDNF), an endogenous signaling molecule, is involved in the carcinogenesis of glioma, especially in tumor growth and metastasis in neuroblastoma, whereas a precursor of BDNF (proBDNF) plays a role in the modulation of cell apoptosis." (PMID 41031155, 2025). "In addition, BDNF activation of the Akt pathway increased neuroblastoma cell proliferation and decreased ropicavine-induced apoptosis by increasing Bcl-2 and PCNA expression and decreasing Bax and cleaved caspase-3 expression." (PMID 40430064, 2025). "In this study, we identified PA-linked changes in the class I histone deacetylases (HDACs) content associated with chromatin acetylation and with differential expression of the BDNF-encoding gene and the non-coding retrotransposon, LINE1 in differentiated human neuroblastoma cells." (PMID 40586999, 2025). "The results from the present study suggest BDNF expression can be increase up to ~8-fold by treating the neuroblastoma cells SHSY-5Y with an herbal extract of Oroxylum indicum (50 μg/mL) and ~5.5-fold under lipopolysaccharides (LPS)-induced inflammation conditions." (PMID 38931243, 2024). "Recent reports also suggest that BDNF/TrkB pathway plays a role in neuronal tumors, such as neuroblastoma, and may have oncogenic effects in various cancers, including lung, breast, and prostate." (PMID 38592583, 2024). "Furthermore, increased BDNF and TrkB signaling in neuroblastoma cells can act as a self‐secretion system promoting tumor growth, invasion, and metastasis." (PMID 39648800, 2024). "The aim of this study was to investigate the effects of three synthetic peptides, i.e., KLVFF, RGKLVFFGR and RIIGL, on an AD in vitro model represented by differentiated SH-SY5Y neuroblastoma cells exposed to retinoic acid (RA) and brain-derived neurotrophic factor (BDNF)." (PMID 39035166, 2024). "However, in neuroblastoma cells, Y5R antagonists blocked the pro-survival effect mediated by BDNF (which favors NPY/Y5R expression/NPY release), promoted apoptosis, and sensitized resistant tumor cells to chemotherapy." (PMID 37373115, 2023). "In this study, we aimed to investigate how ES delivered along aligned or non-aligned nanofibrous scaffolds could modulate the expression of BDNF in SH-SY5Y human neuroblastoma cells." (PMID 37259290, 2023). "Stimulus-evoked induction of Arc expression and dimer formation was first demonstrated in SH-SY5Y neuroblastoma cells treated with the muscarinic cholinergic agonist, carbachol, and in primary cortical neuronal cultures treated with brain-derived neurotrophic factor (BDNF)." (PMID 37363319, 2023). "Indeed, the addition of BDNF promotes molecular polarization in differentiating neuroblastoma cells leading to definitive neurons, which show an enrichment of MAP2 in the dendrite and tau in axons." (PMID 37627228, 2023).
neuroblastoma (continued). "Here, we describe how electrical stimulation delivered along nanofibrous scaffolds could modulate the expression of BDNF in SH-SY5Y human neuroblastoma cells." (PMID 37259290, 2023). "Furthermore, ATRA [X] treatment restores brain-derived neurotrophic factor (BDNF) dependence of neuroblastoma cells, and a BDNF-dependent increase in amyloid precursor protein (APP) gene expression was also observed." (PMID 37247782, 2023). "Moreover, under pro-apoptotic conditions, NPY/Y5R was upregulated in neuroblastoma cells (in a BDNF-independent manner)." (PMID 37373115, 2023). "Enhanced expression of endogenous Arc dimer was observed following carbachol (Cch) treatment of SH-SY5Y neuroblastoma cells, BDNF treatment of cortical neuronal cultures, and LTP induction in the dentate gyrus (DG) of anesthetized rats, where increases of more than 20-fold were demonstrated." (PMID 37363319, 2023). "We explored the possibility that human SH-SY5Y neuroblastoma cells grown on nanofiber scaffolds could be enticed to upregulate their expression of BDNF following ES." (PMID 37259290, 2023). "Thus, the survival NPY/Y5R system is activated by BDNF, and Y5R increases the pro-survival action of this factor and mediates an additional BDNF-independent anti-apoptotic activity contributing to the chemoresistance of neuroblastoma cells." (PMID 37373115, 2023). "The impact of PEM and BDNF on neuroblastoma viability was studied using Alamar Blue® assay." (PMID 37864014, 2023). "Furthermore, APZ exhibited its neuroprotective properties in SH-SY5Y human neuroblastoma cells by increasing both BDNF and Bcl-2 levels." (PMID 38256307, 2023). "Moreover, recombinant MIF administration is effective for inducing the expression of brain-derived neurotrophic factor and promotes neuroprotection of neuronal cells in human neuroblastoma cell lines under oxygen-glucose deprivation." (PMID 35324982, 2022). "BDNF had been found in neuroblastoma, and TrkB had been shown to mediate chemotherapy resistance." (PMID 36120557, 2022). "Treatment with BDNF attenuated cisplatin-induced cell death and decreased the chemosensitivity of neuroblastoma cells to cisplatin, an effect that was blocked by cell treatment with the PI3K inhibitor, LY294002, suggesting a role of PI3K in BDNF’s rescue effects." (PMID 36361620, 2022). "However, due to the high cytotoxicity of EA twig extract against SH-SY5Y cells, we used an in vitro neuronal-derived cell model, B35 neuroblastoma cells to determine the direct effects of EA twig extract 1 and 2 on cholinergic and BDNF/CREB signaling." (PMID 36615789, 2022). "If added to human neuroblastoma cells, Milmed yeast promoted the expression of BDNF and NGF mRNAs." (PMID 36551872, 2022). "In conclusion, DLX6‐AS1 promoted neuroblastoma progression by regulating miR‐107/BDNF pathway." (PMID 35592755, 2022). "Therefore, we used the SH-SY5Y neuroblastoma cell line, in which neuronal differentiation was induced with retinoic acid and brain-derived neurotrophic factor (BDNF)." (PMID 35030990, 2022). "In our previous report, we showed that Milmed yeast addition to human SK-N-SH neuroblastoma cells promoted the expression of BDNF and NGF, confirming that Milmed co-treatment may be suitable for several neurologic and neuropsychiatric disorders." (PMID 36551872, 2022). "Thus, it was shown that the silver nanoparticles produced a significant decrease in various monoamine neurotransmitters, including GABA, levels in the rat brain homogenate and also inhibited BDNF signalling in the human neuroblastoma cell line SH-SY5Y." (PMID 33628375, 2021). "Conversely, in primary neuroblastomas TrkB-FL expression has been found to be associated with MYCN gene amplification, an unfavorable prognostic marker, and its activation by BDNF has been shown to promote neuroblastoma cell survival, resistance to chemotherapy, anoikis and metastasis." (PMID 34360553, 2021). "The first described role of BDNF/TrkB in cancer was in neuroblastoma." (PMID 34395067, 2021).
neuroblastoma (continued). "Additionally, Aβ at a sublethal concentration downregulates BDNF signaling in cultured cortical neurons, while BDNF was shown to be neuroprotective against Aβ-induced apoptosis in neuroblastoma cells." (PMID 34204299, 2021). "Besides, it has been reported that BDNF can stimulate the phosphorylation of FoxO3a by activation of the PI3K/AKT pathway in human neuroblastoma SH-SY5Y cells and a similar regulatory effect was found on primary cultured neurons in our previous studies." (PMID 34721013, 2021). "Furthermore, inhibition of CAMKII prevented BDNF release from neurons while chronic inhibition of GSK-3 reduced accumulation of BDNF in culture media of neuroblastoma cells." (PMID 32944867, 2020). "Additionally, ERK kinase inhibitor blocks BDNF-induced neurite outgrowth in neuroblastoma cell line SH-SY5Y." (PMID 31607850, 2019). "Interestingly, pridopidine has been shown to increase BDNF expression in vivo and in a neuroblastoma cell line; the latter effect was also blocked by NE-100." (PMID 29692729, 2018). "The sigma-1 receptor also mediates pridopidine-induced BDNF in rat neuroblastoma cells." (PMID 29783994, 2018). "In the present study, we focused on the effects of propolis on the hydrogen peroxide- (H2O2-) induced oxidative stress, and expression of BDNF and Arc using cultured human neuroblastoma SH-SY5Y cells, which are widely used for the study of neurodegenerative damage in vitro." (PMID 28265338, 2017). "In the present study, we investigated the effects of propolis on oxidative stress, expression of brain-derived neurotrophic factor (BDNF), and activity-regulated cytoskeleton-associated protein (Arc), the critical factors of synapse efficacy, using human neuroblastoma SH-SY5Y cells." (PMID 28265338, 2017). "In addition, overexpression of either PGC-1α or FNDC5 reversed the suppressive effects of the Aβ1−42 oligomers on the expression of BDNF in neuroblastoma 2a (n2a) cells." (PMID 28377712, 2017). "However, whereas neuronal activity does not affect Psen1 mRNA levels in cortical neurons, glutamate and BDNF activate Psen1 expression in a CREB-dependent manner in neuroblastoma cells." (PMID 29269871, 2017). "Moreover, BDNF has been shown to promote non-small lung cancer proliferation in an autocrine manner and metastasis of neuroblastoma through STAT3 and PI3K and MAPKsingalling pathway, respectively." (PMID 28604807, 2017). "In this study, we tested the hypothesis that cisplatin might induce drug resistance in one aggressive MYCN-amplified neuroblastoma by affecting the regulation of endogenous BDNF levels." (PMID 27256407, 2016). "Thus, the 22% of neuroblastoma cells remaining in the culture after the combined cisplatin+PHA-680632 treatment showed a paradoxical increase in BDNF." (PMID 27256407, 2016). "Recently, several studies have suggested that BDNF and/or its receptor, tropomyosin related kinase B (TrkB), are involved in tumor growth and metastasis in several cancers, including prostate cancer, neuroblastoma, pancreatic ductal carcinoma, hepatocellular carcinoma, and lung cancer." (PMID 27456333, 2016). "Although their combined use show increased activity in the induction of neuroblastoma cell death, specific attention should be paid to the possibility that they could lead to the selection of resistant cells expressing high BDNF levels." (PMID 27256407, 2016). "Finally, we evaluated the BDNF protein production in the neuroblastoma cells which survived the combined treatment." (PMID 27256407, 2016). "We hypothesized that by reducing aurora kinase A activity we may enhance the cytotoxic effect of cisplatin by overcoming the increased production of BDNF in surviving neuroblastoma cells, as a consequence of reduced aurora kinase-dependent BDNF translation." (PMID 27256407, 2016).
neuroblastoma (continued). "Evidence also suggests that PI3K/Akt is activated downstream of Gastrin-Releasing Peptide (GRP)/Gastrin-Releasing Peptide Receptor (GRPR) and Brain-derived neurotrophic factor (BDNF)/TrkB signaling, which are reported to be overexpressed in human neuroblastoma." (PMID 26793165, 2015). "Importantly, the BDNF-polySia complex can bind the BDNF receptors to upregulate growth and survival of neuroblastoma cells." (PMID 25146846, 2015). "Nicotine has induced SH-SY5Y neuroblastoma cell proliferation through BDNF and its receptor, TrkB." (PMID 24782766, 2014). "Finally, we measured the levels of PYY and GLP-1 in plasma from prebiotic-fed rats, and tested their effect on BDNF release from SH-SY5Y neuroblastoma cells." (PMID 24140431, 2013). "Indeed, the BDNF transcript levels in neuroblastomas with a poor prognosis were 2-fold higher as compared to those in tumors with good outcomes." (PMID 22911740, 2012). "In the current study, we showed that Bim expression was reduced in CDDP-resistant HNSCC and exogenous administration of BDNF resulted in reduced Bim expression, a finding that is consistent with effects seen in various disease models including neuroblastoma model." (PMID 22276165, 2012). "Consistent with previous studies in neuroblastoma, BDNF/TrkB signaling in uterine sarcoma may play a role in the acquisition of drug resistance." (PMID 22911740, 2012). "BDNF has been shown to enhance the survival of both myeloma and B-cell lines after serum deprivation whereas, anti-BDNF Ab decreased tumor growth in myeloma and neuroblastoma models." (PMID 21966426, 2011). "BDNF has also been associated with several human cancers, both neuronal and non-neuronal, including: neuroblastoma, myeloma, ovarian, lung, prostate, hepato-cellular, pancreatic, head and neck squamous cell carcinomas and pulmonary carcinoid tumours." (PMID 21767406, 2011). "In addition, inhibition of AKT activation can prevent BDNF mediated protection of neuroblastoma cells from chemotherapy induced apoptosis." (PMID 20409325, 2010). "Therefore, total BDNF mRNA and distinct BDNF transcript levels were measured by semi-quantitative PCR after treatment with different antidepressant drugs in human neuroblastoma SH-SY5Y cells." (PMID 18601743, 2008). "Based on its function in neuroblastoma tumors, we hypothesize that BDNF and TrkB expression in differentiating sympathoblasts is responsible for expanding the neuronal population through proliferation." (PMID 17309801, 2007). "A study examined whether Akt is required and sufficient to mediate brain-derived neurotrophic factor (BDNF)/TrkB protection of neuroblastoma cells from chemotherapy." (PMID 19384426, 2007). "BDNF also promotes the proliferation of cultured neuroblastoma cells." (PMID 17309801, 2007). "Interestingly, previous literature pointed out that SH-SY5Y human neuroblastoma cells, when differentiated by combined treatment with brain-derived neurotrophic factor (BDNF) and retinoic acid, clearly express mRNA for NR1, NR2C, and NR2D, with very weak expression of NR2A mRNA." (PMID 40559208, 2025). "The BDNF/TrkB pathway may also be crucial in inducing angiogenesis in neuroblastoma." (PMID 39648800, 2024). "Consequently, to determine whether hnRNPA2/B1-mediated regulation of ATP7A occurred during neuronal differentiation, SH-SY5Y neuroblastoma cells were differentiated using a two-step protocol using RA and then BDNF treatments." (PMID 36545508, 2022). "Thus, we investigated the suitability of negatively and positively charged PAMAM dendrimers and PAMAM- and PEGylated PAMAM-based nanoparticles with differently charged PAMAM cores to effectively transport BDNF to differentiated neuroblastoma cells exposed to 6-OHDA." (PMID 34454520, 2021). "Furthermore, oligomeric Aβ reduced BDNF exon IV transcripts in human neuroblastoma cells in vitro." (PMID 34071978, 2021).